CCL2 (C-C motif chemokine ligand 2)
Diseases named in the same sentence as CCL2 in open-access papers (continued):
Sharing a sentence is not in itself a finding about the gene and the disease.
breast tumor (continued). "Intravenous administration of CCL2 to mice with xenograft human breast tumours increased metastasis to the lungs and bone, and an increase in macrophage infiltration to these sites." (PMID 34771552, 2021). "In nude mice bearing MCF10CA1d breast tumor xenografts, continuous delivery of human CCL2-neutralizing Ab (0.3 mg/kg/day using osmotic pumps) was analyzed over 4 weeks." (PMID 33540898, 2021). "We found that CCL2 mRNA levels are significantly upregulated in Claudin-low type cancer in the METABRIC dataset of 2509 primary breast tumors with 548 matched normal samples." (PMID 32455851, 2020). "This was evidenced by a CCL2-promoted formation of primary and secondary tumor spheroids that contained more self-renewing CSCs, and by the fact that stimulation of breast tumor cells with CCL5 increased the CD44+/CD24− sub-population." (PMID 32582148, 2020). "Within the breast tumor microenvironment, CCL2 expression by CAFs has been shown to enhance macrophage recruitment and promote cancer cell proliferation and cancer stem cells." (PMID 32731354, 2020). "In breast tumor bone metastases, CCL2 overexpression led to enhanced osteolysis and the release of bone matrix-bound angiogenic factors, including platelet-derived growth factor, fibroblast growth factors-1, and transforming growth factor b." (PMID 32471499, 2020). "We observed a significant increase in LOX and CCL2 expression in the lungs of mice bearing triple-negative SUM159 breast tumors relative to lungs from mice bearing luminal A MCF7 tumors or tumor-naïve mice." (PMID 31936750, 2020). "We have previously reported that breast tumors with a high content of CCL2 or CCL4 had a higher infiltration of B and T lymphocytes." (PMID 32727083, 2020). "We have previously characterized a Human-In-Mouse (HIM) model to study how inflammation driven by CCL2 impacts breast tumor development and progression in vivo." (PMID 32731354, 2020). "In rat breast tumor tissues of IT groups, the mRNA expression of CCL2 and IL18 are significantly down-regulated, in contrast with the up-regulated expression of these cytokines in tumor tissues of the INT group." (PMID 32695310, 2019). "The correct reference is “Qian, B.Z.; Li, J.; Zhang, H.; Kitamura, T.; Zhang, J.; Campion, L.R.; Kaiser, E.A.; Snyder, L.A.; Pollard, J.W. CCL2 recruits inflammatory monocytes to facilitate breast-tumour metastasis." (PMID 31146450, 2019). "Reference 104 to “Qian, B.Z.; Li, J.; Zhang, H.; Kitamura, T.; Zhang, J.; Campion, L.R.; Kaiser, E.A.; Snyder, L.A.; Pollard, J.W. CCL2 recruits inflammatory monocytes to facilitate breast-tumour metastasis." (PMID 31146450, 2019). "This study aims to elaborate on the association of CCL2, IL18, IL23α, and TNF-α (tumor necrosis factor-alpha) expression with the anti-proliferative effect of ECCT in rat breast tumor tissue." (PMID 32695310, 2019). "In our study, human breast tumor sections from 57 patients were stained for CCL2 and Twist using IHC." (PMID 29934505, 2018). "CCL2 was delivered intranasally in mice to elevate CCL2 levels in the lung and effects on seeding and growth of breast tumor cells were evaluated." (PMID 28143493, 2017). "TNFα acts on breast tumor TNF receptors evoking the release of chemotactic proteins (e.g. MCP-1/CCL2)." (PMID 28441391, 2017). "Ca-TAT/siRNA complexes targeting CCL2 were delivered to mice bearing MDA-MB-231 breast tumor xenografts." (PMID 27283985, 2016). "CCL2 antibody neutralization inhibited tumor progression in mice bearing 4T1 or MDA-MB-231 breast tumor xenografts." (PMID 27283985, 2016). "Taken together, silencing of CCL2 gene expression results in decreased breast tumor cell proliferation, and increased necrosis and autophagy." (PMID 27283985, 2016). "By immunohistochemistry analysis of MDA-MB-231 breast tumor xenografts, we observed a significant reduction in ALDH1 expression in CCL2 deficient tumors." (PMID 27283985, 2016).
breast tumor (continued). "Previous studies have shown that macrophages express CCL2, and have suggested that CCL2 regulates macrophage recruitment to primary breast tumors through a positive feedback loop." (PMID 27283985, 2016). "CCL2 is expressed in various cancers, including breast tumors, and is considered a tumor-derived chemotactic factor for diverse immune cell types." (PMID 25882816, 2015). "CCL2 was expressed in CAFs residing in proximity to breast tumor cells in biopsies of patients diagnosed with invasive ductal carcinoma." (PMID 25928089, 2015). "The findings presented in this study indicate that oncogenic events, such as hyper-activation of the Ras pathway, exacerbate the release of pro-malignancy chemokines (e.g., CXCL8 and CCL2) by MCF-7 human breast tumor cells." (PMID 24598028, 2014). "This lack of coordination between CCL2 & CCL5 and TNFα & IL-1β in this sub-population is intriguing mainly because TNFα and IL-1β were found to stimulate the release of CCL2 and CCL5 by breast tumor cells." (PMID 21486440, 2011). "In that study, the authors suggested that this TNF/CCL-2 axis could yield pro-cancerous myeloid infiltrates in breast tumors." (PMID 40362499, 2025). "In vivo knockdown of breast tumor-derived CCL2 partially protected against SMW." (PMID 38973385, 2024). "In human breast tumors, inflammatory mononuclear cells (IMCs) are recruited by binding chemokine (C-C motif) ligand 2 (CCL2), which is synthesized by tumor and stromal cells, to chemokine receptor 2 (CCR2), which promotes neovascularization and tumor cell infiltration." (PMID 39544302, 2024). "As breast tumor tissues and cells chronically overexpress CCL2, we hypothesized that increased CCL2 levels would adversely affect muscle cells." (PMID 38973385, 2024). "During the in vitro conversion process of mesenchymal stromal cells in cancer-associated fibroblast by breast tumor cell (MDA-MB-231 and MCF-7)-conditioned media, TNF-alpha stimulation is responsible for the chemokines released (CCL2, CXCL8, and CCL5) by the tumor stromal cells." (PMID 37681908, 2023). "Moreover, we found that TNC expression sustains CCL2 expression in breast tumor cells, both in vivo and in vitro, consistent with a link between these molecules in other disease models and cell types." (PMID 37176074, 2023). "Furthermore, IHC staining for PTEN and CCL2 in human primary breast tumors and matched brain metastases revealed significantly higher CCL2 expression in brain metastases than in primary tumors." (PMID 37208442, 2023). "Furthermore, CCL2 expression is higher in metastatic breast tumors compared to primary breast tumors." (PMID 36403055, 2022). "Furthermore, blocking IL-1β can reduce the recruitment of monocytes mediated by CCL2, decrease the infiltrating macrophages in the tumor microenvironment, and prevent breast tumor growth." (PMID 36403055, 2022). "Furthermore, as inhibition of CCL2 signaling reduced the growth of breast tumor xenografts and decreased stem cell activity, cancer stem cell activity is not likely to be a factor." (PMID 35405500, 2022). "Together, these results suggest that targeted inhibition of fibrocytes may reduce CCL2-induced desmoplasia within breast tumors to enhance chemotherapeutic efficacy." (PMID 32731354, 2020). "To understand how CCL2-induced inflammation alters breast tumor pathology, we transplanted oncogenically transformed human breast epithelial cells with breast stromal cells expressing CCL2 or empty vector into murine mammary glands and examined tumor formation and progression with time." (PMID 32731354, 2020). "Furthermore, CCL2 derived from fibroblasts is important for enhancing breast tumor growth, invasion and metastasis." (PMID 31208996, 2019). "Indeed, our findings are supported by previous experimental studies demonstrating the CCL2 levels of breast tumors correlated significantly with serum estrogen levels." (PMID 29934505, 2018).
breast tumor (continued). "CCL2 recruits CCR2-expressing inflammatory monocytes to facilitate breast tumor metastasis." (PMID 30151375, 2018). "MCP-1 mRNA expression was enhanced when stromal cells were co-cultured with breast tumor cells, and when immune deficient mice received blocking antibodies to MCP-1 (CCL2), there was a reduction in angiogenesis, macrophage infiltration into the tumors and also the growth of the tumors slowed." (PMID 28143493, 2017). "In addition, studies have shown that treatment of breast tumor xenografts with neutralizing antibodies to CCL2 lead to increased expression of IL-6 and VEGF when anti-CCL2 treatment was interrupted." (PMID 27283985, 2016). "Diallyl disulfide reversed TNF-α-induced CCL2 release in human breast tumor (MDA-MB-231) cells." (PMID 27529277, 2016). "In functional studies, CCL2 antibody neutralization in 4T1 or MDA-MB-231 breast tumor xenografts inhibited tumor growth and metastasis, while decreasing the levels of macrophages in the primary tumors, indicating that CCL2 promotes progression of TNBC through macrophage dependent mechanisms." (PMID 27283985, 2016). "Exposure of MSCs to TNF-α led to potent CCL2-induced migration of monocytic cells, a process that may yield pro-cancerous myeloid infiltrates in breast tumors." (PMID 25928089, 2015). "To this end, we determined the influence of breast tumor-derived factors and of inflammatory cytokines on the inflammatory phenotype of CAFs and MSCs, manifested by the release of the pro-cancerous chemokines CCL2, CXCL8 and CCL5 by these cells." (PMID 25928089, 2015). "Monocyte chemoattractants CCL5 and CCL2 secreted by breast tumor cells may induce monocyte infiltration to the microenvironment of breast tumors." (PMID 22408433, 2012). "A recent study also showed that overexpression of TILRR in BT474, a human breast tumor cell line, significantly potentiates the expression of immune and inflammation-associated genes, including IL-6, IL-8/CXCL8, IP-10 (interferon gamma-induced protein 10)/CXCL10, MCP-1/CCL2, and RANTES/CCL5." (PMID 34360591, 2021). "While there are some potential anti-tumor effects of CCL2 in vitro and in vivo during early tumor formation, there are strong data from many groups, including the data reported here, indicating that intra-tumoral CCL2 can promote breast tumor growth and/or metastases." (PMID 28143493, 2017). "In breast tumor tissue, MCs can be recruited by chemokines such as monocyte chemoattractant protein-1 (MCP-1/CCL2) and regulated on activation, normal T cell expressed and secreted (RANTES), as well as by the cytokine colony-stimulating factor (CSF)." (PMID 41596472, 2026). "In human prostate and breast tumors, the CH25H gene shows a very high correlation of coexpression with the CCL2 and CCL8 genes, as is the case in the dormant‐met group." (PMID 41159143, 2025). "The higher expression of the chemokine CCL2/Monocyte chemoattractant proteins (MCP-1) and its receptor CCR2 is related to the primary breast tumor cells undergoing malignant transformation, and it was found to be expressed by the multiple cells of TME." (PMID 39125273, 2024). "This appears to be the case in the present studies where IOA-289 decreased the plasma concentrations of CCL2, CXCL9, and CXCL10, together with its effect of inhibiting the growth of E0771 breast tumors." (PMID 37296899, 2023). "Following CCL2 expression, the present result demonstrated that IL18 expression is downregulated in breast tumor tissue exposed to ECCT treatment." (PMID 32695310, 2019). "Instead, we observed that E2 significantly increased the levels of CCL2 in ER+ MCF-7 and T47D cells as well as serum from nude mice bearing ER+ implanted breast tumors." (PMID 29934505, 2018). "Further analysis revealed IL-6, CCL2, and MMP9 were upregulated in breast tumors with low compared to high IGF-1R." (PMID 30458886, 2018).
breast tumor (continued). "This experimental design allowed us to examine the ability of exogenous CCL2 to enhance the ability of naïve neutrophils or TEN to kill luciferase expressing aggressive and less aggressive breast tumor cells." (PMID 28143493, 2017). "Together, these findings suggest that tumors containing high levels of TNFα and TGFβ1 are enriched with the inflammatory and tumor-promoting mediators CCL2, CXCL8 and Cox-2, and that all three inflammatory mediators are coregulated in human breast tumors." (PMID 28553282, 2017). "In one study, these inflammatory cytokines alongside with inflammatory chemokines; CCL2 and CCL5 are expressed in a coordinated fashion which provides a combined role of the mediators to supports the growth and progression of breast tumor." (PMID 27558166, 2016). "While the expression of CCL2, CCL5, TNFα or IL-1β was only minimally detected in infiltrating leukocytes of all groups of patients, the four factors were clearly observed in breast tumor cells, with mainly a cytoplasmic staining pattern." (PMID 21486440, 2011). "CCL2 expression was significantly increased in luminal B breast tumors and tumors in MMTV-PyMT or MMTV-Neu mice compared to normal breast tissue or luminal A breast tumors." (PMID 37208442, 2023). "The cancer-associated membrane glycoprotein dysadherin facilitates the invasion of tumor cells into the Matrigel in estrogen receptor (ER)-negative breast tumor cells through controlling CCL2 production in vitro and lung metastases in an in vivo animal model." (PMID 37373025, 2023). "No statistic correlation was observed between breast tumor tissue miR-21 expression levels and those of CCL-2, RANKL and MMP-9, probably due to the low number of samples." (PMID 36890825, 2023). "Meanwhile, the weight and size of primary breast tumor cells were also evaluated, we found the absence of CCL2 would reduce the more than 4 folds of tumor weight." (PMID 34249913, 2021). "In our analysis of the TCGA breast tumor cohort, we observed significant positive correlations between TREM1 expression and the expression of TREM-1 target cytokines (IL1B, IL8, IL6 and CCL2) and markers of MDSCs and TAMs (CD11B/ITGAM, OLR1, CD14 and CD206/MRC1)." (PMID 34956864, 2021). "For example, a CCL2 antibody has been used to neutralize CCL2 secreted by cancer and stromal cells to inhibit the recruitment of inflammatory monocytes and MAM accumulation in breast-tumor metastases." (PMID 32326073, 2020). "Therefore, our result suggested that decreasing CCL2 and IL18 expression in the breast tumor microenvironment is most probably due to AC-EF treatment." (PMID 32695310, 2019). "In contrast to CCL2 antibody neutralization of breast tumor xenografts, CCL2 gene silencing did not increase tumor cell apoptosis or affect tumor angiogenesis." (PMID 27283985, 2016). "The inter-connection between CCL2 & CCL5 and TNFα & IL-1β in the immune setting suggests that similar interactions exist between these chemokines and cytokines also within the inflammatory context of breast tumors." (PMID 21486440, 2011). "Indeed, our findings and published studies indicate that TNFα and IL-1β up-regulate the release of CCL2 and CCL5 by breast tumor cells." (PMID 21486440, 2011). "Such a cross-talk may lead to up-regulated expression of CCL2 and CCL5 in tumors expressing TNFα and/or IL-1β, thus possibly leading to increased tumor-supporting activities of the two chemokines in breast tumors (see Discussion, below)." (PMID 21486440, 2011). "Ly6Chi inflammatory monocytes are preferentially recruited to metastatic sites by Ccl2 (which is also highly expressed in the MOSE-LTICv) and allow for tumor cell extravasation and metastasis while residential monocytes (Ly6Clo) were found mostly in primary breast tumors." (PMID 38264656, 2023). "However, exogenous CCL2 did not enhance naïve or TEN neutrophil killing of more aggressive 4T1 or PyMT breast tumor cells." (PMID 28143493, 2017).
breast tumor (continued). "Interestingly, the inhibition of CCL2 action in metastatic breast tumor significantly diminished the size of metastasis in the lungs and macrophage accumulation in cancer in mice but did not alter the primary breast tumor’s size." (PMID 35408440, 2022). "However, there was no direct evidence that CCL2 could directly promote lung metastasis by recruiting such cells in the primary breast tumor." (PMID 34249913, 2021). "Expression of CCR2, the main CCL2 receptor, in both TNC+ and TNC− NT193 breast tumor cells was below 0.5% of HPRT for all timepoints in both cell types, suggesting that whilst tumor cells are a major source of CCL2, they are not responding in an autocrine manner to this chemokine." (PMID 37176074, 2023). "Also, preliminary analyses that we have performed indicated that CCL2 and CCL5 were not capable of inducing EMT-related processes in the breast tumor cells (data not shown)." (PMID 21486440, 2011).